PLK1 (polo like kinase 1)
Diseases named in the same sentence as PLK1 in open-access papers (continued):
Sharing a sentence is not in itself a finding about the gene and the disease.
melanoma (continued). "Herein, we show that some melanoma cell lines, such as MeWo, possess intrinsic resistance towards PLK1 inhibition, without the need to establish resistant cell lines." (PMID 39658088, 2025). "Taken together, our results demonstrate that PLK1 promotes melanoma development and progression through BACH1, while the depletion of BACH1 could abolish the PLK1-induced phenotypes in melanoma." (PMID 41284701, 2025). "Our analyses also indicate that basal profiling of mitochondria (mtDNA content, expression of OXPHOS proteins, respiration) does not correlate with the sensitivity to RSK/PLK1 inhibition in six melanoma cell lines." (PMID 39658088, 2025). "Moreover, the PLK1/BACH1 axis confers resistance to Vemurafenib, a BRAFV600E inhibitor, in melanoma." (PMID 41284701, 2025). "We found that compared to normal skin, the expression of PLK1 was significantly increased in both non-sun-exposed and sun-exposed melanoma." (PMID 41284701, 2025). "Taken together, these results suggest that specific expression patterns of mitochondrial proteins may be responsible for the sensitivity and inflammatory profiles of melanoma cells in response to RSK and PLK1 inhibitors." (PMID 39658088, 2025). "Further, using in vitro experiments with PLK1 overexpression, knockdown, and kinase active (T210D)/inactive (K82R) modulations in multiple melanoma cell lines, we found that both PLK1 expression and kinase activity are important in promoting cell migration, invasion and EMT in melanoma." (PMID 38184733, 2024). "By disrupting cell cycle progression and inducing DNA damage, TYMS may alter PLK1 expression and activity, affecting processes such as proliferation, apoptosis, and EMT in melanoma." (PMID 39353904, 2024). "Furthermore, we revealed that the combination of the PLK1 inhibitor volasertib (BI6727) with 5-FU or CAP had a synergistic effect repressing the proliferation, migration, and autophagy of melanoma cells." (PMID 39353904, 2024). "However, the exact role of PLK1, NUMB, and NOTCH signaling in epithelial-mesenchymal transition (EMT) in melanoma progression is unclear." (PMID 38184733, 2024). "Our findings support the therapeutic targeting of PLK1, NUMB, and NOTCH for melanoma management." (PMID 38184733, 2024). "Altogether, our study suggests that targeting PLK1, NUMB, and NOTCH may be a potential therapeutic strategy in inhibiting melanoma progression." (PMID 38184733, 2024). "Overall, our Affymetrix microarray data indicated that PLK1 might be an important signaling molecule involved in EMT and metastasis-related functions in melanoma." (PMID 38184733, 2024). "To examine how the combined expressions of PLK1-NUMB, NOTCH-NUMB, PLK1-N-cadherin and PLK1-E-cadherin affect overall survival (OS) of melanoma patients, we downloaded the RNA-Seq gene expression and clinical data for a total of 479 patients from The Cancer Genome Atlas (TCGA) melanoma data set21." (PMID 38184733, 2024). "However, the exact role and significance of PLK1, NUMB, and NOTCH in melanoma remains to be determined." (PMID 38184733, 2024). "Interestingly, three of these identified pathways were, i) cancer metastasis signaling, ii) HOTAIR regulatory pathway, and iii) regulation of EMT pathway, suggesting a potential role of PLK1 in EMT and melanoma metastasis." (PMID 38184733, 2024). "NOD2 may affect the biological behavior of melanoma cells by regulating the expression and activation status of TYMS and PLK1." (PMID 39353904, 2024). "Therefore, this study highlights the therapeutic significance of targeting PLK1, NUMB, and NOTCH in the clinical management of melanoma." (PMID 38184733, 2024). "In addition, it was revealed that PLK1 and NOTCH inhibitors had synergistic antiproliferative effect on multiple human melanoma cells." (PMID 37259298, 2023). "Interestingly, a chemical compound screen identified the Polo Like Kinase 1 (PLK1) inhibitor and RAS mimetic, Rigosertib, as being synthetically lethal with USP28 downregulation in melanoma cells." (PMID 31416288, 2019).
melanoma (continued). "Similarly, the increased metastatic ability could be observed in the human melanoma cell line A375 and SK-MEL-28 with overexpressed PLK1." (PMID 41284701, 2025). "Overall, we have discovered a novel function of PLK1 that is independent of the cell cycle, which could pave new ways for melanoma therapies." (PMID 41284701, 2025). "Hence, the observed decreased migratory (at 48 h) and invasive (at 24 h) behavior appears to be due to PLK1 knockdown rather than due to a decrease in the proliferation of melanoma cells." (PMID 38184733, 2024). "NOD2 may function in melanoma by regulating the expression and activities of TYMS and PLK1." (PMID 39353904, 2024). "Importantly, we observed that shRNA-mediated PLK1 knockdown in A375, WM115, and SK-MEL-2 cells (human melanoma cell lines that possess high metastatic potential) inhibited cell migration and invasion, as well as modulated the expression of EMT-related proteins." (PMID 38184733, 2024). "Therefore, the observed increased migratory (at 48 h) and invasive (at 24 h) behavior appears to be due to PLK1 manipulation rather than due to an increase in the proliferation of melanoma cells." (PMID 38184733, 2024). "As PLK1 is already upregulated during melanoma progression, further forced overexpression may not be able to produce significant differences to visualize at the molecular level." (PMID 38184733, 2024). "However, the changes in NICD expression and nuclear intensity due to the overexpression of PLK1, and its mutant constructs K82R, and T210D were not consistent in all melanoma cell lines tested." (PMID 38184733, 2024). "Similarly, DEPDC1B SHCBP1, RRM2, PLK1, and UHRF1 have been found to promote melanoma proliferation and could be potential targets for treatment; their coefficients were all positive, which implies that they had an additive effect on the risk scores." (PMID 34384498, 2021). "The coupling of inhibitors against BRAF/MEK, BRAF/JNK, MEK/Plk1, MEK/pan-RAF, and PI3K/MAPK have been explored as promising approaches; however, these strategies only uncover a fraction of the therapeutic potential contained in combinatory treatment of melanoma." (PMID 33807778, 2021). "To determine whether the ability of PLK1 to promote melanoma cell migration, invasion, and EMT was dependent on its phosphorylation activity, we overexpressed constitutively kinase-active (T210D) and kinase-inactive (K82R) PLK1 in A375, WM115, and SK-MEL-2 melanoma cells." (PMID 38184733, 2024). "Thus, we hypothesized that PLK1 has a role in cellular invasion and metastasis by inducing EMT in melanoma cells and PLK1 phosphorylation of NUMB may be an important step in cellular reprogramming causing EMT via activation of the NOTCH pathway in melanoma cells." (PMID 38184733, 2024). "While MITF has been shown to antagonize pro-inflammatory responses through inhibition of NF-κB and AP-1 in melanoma, we did not observe a reduction in MITF and PGC-1α transcript in MeWo cells treated with the RSK/PLK1 inhibitor BI-D1870." (PMID 39658088, 2025). "However, direct evidence supporting the involvement of PLK1 and NUMB in EMT process in melanoma is lacking." (PMID 38184733, 2024). "Overexpression of polo-like kinase 1 (PLK1) is a negative prognostic factor for NSCLC patients and patients suffering from some other solid tumors, like esophageal carcinoma, head and neck tumors and melanoma." (PMID 29383199, 2017). "Additionally, as NUMB is a known NOTCH inhibitor, we analyzed the expression of NOTCH1 using TCGA melanoma patient data and found a non-significant decreasing trend in NOTCH1 expression with PLK1-low/NUMB-high expression when compared to PLK1-high/NUMB-low levels." (PMID 38184733, 2024).
ovarian carcinoma (59 papers, 2004 to 2026). A malignant neoplasm originating from the surface ovarian epithelium. "Analysis of 18 ovarian cancer samples further revealed that higher PLK1 expression was associated with increased sensitivity to PARPis." (PMID 41458961, 2025). "Cancers with BRCA1/2 mutations including TNBC and ovarian cancer demonstrate sensitivity to PLK1 inhibitors like onvansertib." (PMID 38234395, 2023). "This effective triple-combined strategy underlines the potency of PLK1 inhibition in the treatment of ovarian cancer." (PMID 34065956, 2021). "High expression of PLK4/PLK1 on mRNA and protein level is linked to an advanced pathological stage in epithelial ovarian cancer and PLK4-transfected ovarian cell lines show accelerated proliferation." (PMID 34065956, 2021). "A recent report has linked platinum resistance in ovarian cancer to APC/C dysfunction coupled with functional dependency on Polo-like kinase 1 (PLK1) for mitotic exit." (PMID 33542435, 2021). "Overexpression of PLK1 correlates positively with mitotic activity and is a prognostic factor in ovarian carcinoma linked to worse patient prognosis as judged from immunohistochemistry of several malignant epithelial subtypes." (PMID 34065956, 2021). "In a previous study, we observed that an early and significant apoptosis induction by the CPT ST1968 was associated with a marked reduction of PLK1 levels in human squamous and ovarian cancer cell lines." (PMID 25826089, 2015). "In summary, our study demonstrated that casticin-induced dephosphorylation of FOXO3a regulates the expression of FoxM1 and its target genes, including survivin, PLK1 and p27KIP1, and this causes apoptosis in ovarian cancer cells." (PMID 23761826, 2013). "The importance of PLK isoenzymes for mitosis in ovarian carcinoma is underlined by our finding that the expression of both PLK1 and PLK3 correlated with the mitotic activity." (PMID 14970859, 2004). "Furthermore, PLK1 expression has prognostic relevance in ovarian cancer, and its overexpression is associated with poor patient outcomes." (PMID 36142803, 2022). "As accounts for a multitude of other cancers, dysregulation of PLK1 is linked to ovarian cancer." (PMID 34065956, 2021). "Therefore, BRDT-mediated ovarian cancer cell progression is associated with regulation of PLK1 and AURKC expression." (PMID 33257688, 2020). "Polo-like kinase 1 (PLK1) is a key serine/threonine protein kinase found in various cancers, including ovarian cancer." (PMID 41354716, 2025). "Preclinical and early clinical studies have demonstrated the promising antitumor activity of PLK1 inhibitors in ovarian cancer." (PMID 41354716, 2025). "Although current preclinical and clinical data support the potential therapeutic value of targeting PLK1 in epithelial ovarian cancer, several limitations should be acknowledged." (PMID 41458961, 2025). "Volasertib is a more recently developed selective PLK1 inhibitor that had antitumour activity in platinum-resistant ovarian cancer." (PMID 39851561, 2025). "It is demonstrated that the in vivo delivery of the antibody‐CRISPR/Cas nanocomplexes can effectively disrupt the plk1 gene in HER2‐positive ovarian cancer, resulting in substantial suppression of tumor growth." (PMID 38552157, 2024). "Onvansertib, a highly selective PLK1 inhibitor, and olaparib were tested in vitro and in vivo in BRCA1 mutated and wild-type (wt) ovarian cancer models, including patient-derived xenografts (PDXs) resistant to olaparib." (PMID 39039067, 2024). "When systemically injected, Epi-1-LNPs carrying PLK1 siRNA achieved significant inhibition of PLK1 gene expression at tumor sites in a Hep3B xenograft cancer model and an ovarian cancer peritoneal dissemination model." (PMID 38516300, 2023). "It is worth noting that PLK1 inhibitors have shown promising therapeutic effects in triple negative breast cancer and ovarian cancer patients." (PMID 38037110, 2023).
ovarian carcinoma (continued). "The PLK1-positive cell population was significantly higher in stage 3 ovarian cancer than in stage 1 ovarian cancer (P = 0.001)." (PMID 35379935, 2022). "Increased CDCA8 expression in ovarian tissues probably plays a critical role in the development of ovarian cancer through the PLK1 pathway." (PMID 35354488, 2022). "Elevated levels of PLK1/PLK1 mRNA and protein account for ovarian cancer cell lines and tissue and promote growth and migration of cancer cells and diminish apoptosis." (PMID 34065956, 2021). "MiR-545 directly targets PLK1 mRNA and inhibits PLK1 expression in ovarian cancer thereby acting as a tumor suppressor as demonstrated in vitro and in vivo in a xenograft mouse model." (PMID 34065956, 2021). "In a large patient cohort with early-stage ovarian cancer, high PLK1 expression correlates with bad prognosis based on immunohistochemistry." (PMID 34065956, 2021). "The PLK1 gene can be reversibly silenced, as demonstrated in an ovarian cancer cell line, among others." (PMID 34065956, 2021). "BI 2536 was the first selective PLK1 inhibitor used in clinical trials for the treatment of advanced ovarian cancer." (PMID 34065956, 2021). "Aurora borealis (BORA) is highly expressed in aggressive ovarian cancer and exerts its oncogenic role via activation of PLK1 in vitro and in vivo." (PMID 34065956, 2021). "The role of PLK1 in ovarian cancer is a special interest of this review and will be discussed further below." (PMID 34065956, 2021). "Successful treatment of ovarian cancer remains to be a challenge and especially PLK1 and PLK4 proof to be a very promising target for diagnosis and treatment." (PMID 34065956, 2021). "FOXM1, as a transcription factor, regulated many important proliferation-related target genes (AURB, CCNB1, BIRC5, CDC25, and PLK1, etc.)and was important oncogenic driver in ovarian cancer progression." (PMID 34966670, 2021). "We then looked for potential synergistic combinations of PLK1 inhibitors with drugs used in first line treatment of ovarian carcinoma (cisplatin and paclitaxel) and with other investigational drugs (eribulin and PI3K inhibitors)." (PMID 32183025, 2020). "PLK1 expression has been connected with disease prognosis and sensitivity to chemotherapy in ovarian cancer, which presents a potential biomarker or therapeutic target in combating resistance." (PMID 33182737, 2020). "Several studies have shown that PLK1 is overexpressed in a broad spectrum of malignant tumors, including ovarian cancer, and its expression correlates with histological grade and poor prognosis." (PMID 32183025, 2020). "Considering both aspects, we tested the combinatorial inhibition of PLK1 and the microtubule dynamics by paclitaxel in ovarian cancer cells with CCNE1-amplification." (PMID 29899826, 2018). "In ovarian cancer, a significant correlation between PLK1-positive cells and the histological grade was found." (PMID 29899826, 2018). "Together, this set of experiments shows that PLK1 inhibition and paclitaxel cooperate in a synergistic manner to induce apoptosis in ovarian cancer cell lines with CCNE1-amplification based on our Annexin V experiments (combination index <1)." (PMID 29899826, 2018). "The number of PLK1-positive cells was significantly higher in ovarian cancers designated as grade 3 than in cancers designated as grade 1 (P<0.001)." (PMID 29899826, 2018). "To evaluate the role of PLK1 for the stability of FBW7 in ovarian cancer cells, we tested BI6727 for its capacity to trigger the level of FBW7." (PMID 29899826, 2018). "Together, this set of experiments reveals a novel cooperation of PLK1 inhibition and microtubule-targeting drugs like paclitaxel to reduce cell viability in ovarian cancer cell lines with CCNE1-amplification." (PMID 29899826, 2018). "Consistent with our findings, PLK1 was also identified in a recent in vivo shRNA screen in ovarian cancer." (PMID 27558154, 2016).
ovarian carcinoma (continued). "miR-100 also inhibits the expression of the proto-oncogene PLK1 (Polo-like kinase-1) in ovarian cancer." (PMID 23237306, 2012). "Correspondingly, the elevation of PLK-1 expression occurs in a broad range of human tumors, and a close correlation has been documented between mammalian PLK-1 expression and progression of endometrial and ovarian cancers." (PMID 19775446, 2009). "An earlier study carried out on 17 cases of ovarian carcinoma reported an overexpression of PLK1, which correlated positively with tumour stage and tumour grade." (PMID 14970859, 2004). "Preclinical studies on PLK1-targeted therapy for ovarian cancer." (PMID 41458961, 2025). "PLK1 protein levels in ovarian cancer cells also seem to correlate with MYC and HSF1 levels." (PMID 39831777, 2025). "The cell cycle protein PLK1, which promotes mitosis, is often overexpressed in cancer and may predict small-cell lung cancer, colon cancer, ovarian cancer, and HCC." (PMID 36765811, 2023). "Accordingly, we investigated whether PLK1, which is overexpressed in ovarian cancer, confers an adaptive response to HGSOC cells against DNA damaging agents and PARP inhibition." (PMID 36142803, 2022). "Highly expressed PLK1 promotes proliferation and migration of cultured ovarian cancer cells." (PMID 34065956, 2021). "For example, targeting Cyclin E1 by a PLK1 inhibition-based stabilization of FBW7 might be a novel approach to increase apoptosis in CCNE1-amplified ovarian cancer cells." (PMID 32380689, 2020). "Thus, PLK1-AURKC downregulation should be a primary mechanism of BRDT depletion-induced anti-ovarian cancer cell activity." (PMID 33257688, 2020). "Importantly, BRDT-KO-induced anti-ovarian cancer cell activity was largely attenuated with PLK1 and AURKC re-expression." (PMID 33257688, 2020). "Of note, a recent study reported hints of antitumor activity in patients with platinum-resistant or -refractory ovarian cancer treated with volasertib, suggesting PLK1 could be an interesting target to be further investigated in ovarian cancer." (PMID 32183025, 2020). "In combination with other inhibitors, proTAME was shown to be efficient in overcoming resistance caused by the hyperphosphorylation of CDH1 in glioblastoma cells, polo-like kinase 1 (PLK1)-based drug resistance in ovarian cancer cells and CDC20-based resistance in diffuse large B-cell lymphoma." (PMID 31540287, 2019). "In a study on normal ovaries (n=9), cystadenomas (n=17), borderline tumors (n=13) and ovarian carcinomas (n=77), the frequency of PLK1 expression was low in normal epithelium and borderline tumors, but in ovarian carcinomas 26% of the cancer tissues were PLK1-positive." (PMID 29899826, 2018). "Therefore, the application of the PLK1 inhibitor BI6727 sensitized ovarian cancer cells to paclitaxel in a synergistic manner (combination index <1)." (PMID 29899826, 2018). "In previous studies designed to investigate the cell response to a novel Top1 poison, ST1968, we noticed that the susceptibility of human SCC and ovarian cancer cells to an early and significant CPT-induced apoptosis was associated with a marked reduction of the PLK1 protein." (PMID 25826089, 2015). "The overexpression of PLK1 has been found in many human cancers, including ovarian carcinoma." (PMID 22246341, 2012). "Furthermore, this study suggests that PLK1 is a novel independent prognostic marker in ovarian carcinomas." (PMID 14970859, 2004). "In ovarian carcinomas, 26% of cases were PLK1 positive and 50.6% of cases were PLK3 positive." (PMID 14970859, 2004). "We additionally hypothesised that PLK1 expression might serve as an independent prognostic factor in ovarian carcinomas." (PMID 14970859, 2004). "However, we have shown that PLK1 overexpression has independent prognostic significance in ovarian carcinomas." (PMID 14970859, 2004).